YBX1 (Y-box binding protein 1)
Diseases named in the same sentence as YBX1 in open-access papers (continued):
Sharing a sentence is not in itself a finding about the gene and the disease.
lung cancer (continued). "Our analysis of YBX1 expression identified a significant difference between the expression distributions of the male and the female cohorts in the case of lung cancer, which might be related to the stark differences in mortality between sexes." (PMID 38538658, 2024). "In female lung cancer patients, better survival and lower YBX1 expression were identified." (PMID 38538658, 2024). "Utilizing the TCGA database, we found that YBX1 expression is significantly upregulated in lung cancer patients compared with healthy individuals and is positively correlated with overall survival (OS) in lung cancer patients." (PMID 38899362, 2024). "However, our immunofluorescent localization showed that YBX1 enriched in the cytoplasm in lung cancer cells." (PMID 37324942, 2023). "YBX1 also mediates the methylation that promotes the development of lung cancer." (PMID 37500615, 2023). "Our data demonstrate that hY4 RNA fragments were upregulated in lung cancer- derived EVs, hY4F inhibits tumor progression through downregulating MAPK/NF-κB signaling, and then the selective sorting and secretion of hY4F into lung cancer EVs is regulated by the RNA-binding protein YBX1." (PMID 35410432, 2022). "Numerous studies have suggested YBX1 could act as an oncoprotein in a variety of human cancers, including pancreatic cancer, colorectal cancer, lung cancer and nasopharyngeal cancer." (PMID 34991621, 2022). "In addition, transwell assays demonstrated that YBX1 knockdown suppresses lung cancer cell migration and invasion, while overexpression of YBX1 promoted cell migration and invasion." (PMID 35410432, 2022). "The other study demonstrated that linc00312 could promote metastasis and angiogenesis in lung cancer via interacting with the transcription factor YBX1." (PMID 34336850, 2021). "Furthermore, suppression of MIR22HG significantly accelerated lung cancer cell proliferation via YBX1, MET, and p21 in lung cancer." (PMID 34187303, 2021). "Next, we tested whether MUC1 overexpression could rescue lung cancer stem-like properties after YBX1 silencing." (PMID 34976785, 2021). "We identified at least five proteins of interest (NKX2-1, CAV1, YBX1, FN1 and CDH3) with two different machine learning models that may be associated with lung cancer patient survival." (PMID 33086649, 2020). "lncRNA LINC00857 silencing can impair cell proliferation and induce apoptosis and autophagy in lung cancer, which may be through YBX1-MET and p-AMPKa signaling." (PMID 33312753, 2020). "YBX1 appears to be an important factor in lung cancer, and we previously reported that lung cancer cell proliferation was decreased after siRNA knockdown of YBX1, indicating that YBX1 may play an oncogenic role in lung cancer." (PMID 33312753, 2020). "Notably, endogenous CDKL1 was observed to bind to endogenous YBX1 in lung cancer cells." (PMID 38520004, 2024). "Furthermore, findings from reporter luciferase experiments and chromatin immunoprecipitation (ChIP) studies have indicated that YBX1 binds to the Cyclin D1 promoter, enhancing its expression at both the protein and mRNA levels in lung cancer cells and neuroblastoma cells." (PMID 38255791, 2024). "Consequently, lncRNA AATBC may promote lung cancer migration by activating the Hippo pathway through the lncRNA AATBC/YBX1/MST1 axis." (PMID 39313797, 2024). "Next, we studied whether YBX1 plays a vital role in lung cancer progression." (PMID 35410432, 2022). "Mechanistic studies show that NSUN2 regulates the m5C modification of QSOX1, and YBX1 enhances QSOX1 translation in an m5C-dependent manner, thereby promoting resistance to EGFR-mutant lung cancer." (PMID 40370440, 2025).
lung cancer (continued). "The roles of hY4F, YBX1, and SET domain containing 3 in biological functions, such as proliferation, migration, invasion, and apoptosis, in lung cancer cells were also examined by EdU incorporation assay, Transwell assay, flow cytometry, and other methods." (PMID 35410432, 2022). "Our study verified the high correlation between YBX1 and MUC1 expression in lung cancer for the first time, and the results were consistent with those in large databases." (PMID 34976785, 2021). "In previous studies, YBX1 and MUC1 were crucial in predicting the prognosis and recurrence of lung cancer." (PMID 34976785, 2021). "RNA-seq analysis from Oncomine and TCGA found that YBX1 and MUC1 mRNA expression levels in lung cancer tissues were highly correlated, especially in lung adenocarcinoma." (PMID 34976785, 2021). "Silencing of MIR22HG can also triggers cell survival/death signaling via oncogenes YBX1, MET, and p21 in lung cancer." (PMID 32127004, 2020). "LINC00312 directly interacts with the transcription factor Y-Box Binding Protein 1 (YBX1) to facilitate migration, invasion and vasculogenic mimicry of lung cancer cells." (PMID 31728180, 2019). "CAR10 binds to and stabilizes TF Y-box-binding protein 1 (YB-1), leading to up-regulation of EGFR and proliferation of lung cancer cells." (PMID 27397102, 2016). "CAR10 bound and stabilized transcription factor Y-box-binding protein 1 (YB-1), leading to up-regulation of the epidermal growth factor receptor (EGFR) and proliferation of lung cancer cells." (PMID 27322209, 2016). "Moreover, CircRABL2B interacts with YBX1 to inhibit MUC5AC, thereby regulating lung cancer stemness and drug sensitivity." (PMID 40799245, 2025). "Additionally, YBX1 directly promotes the transcriptional activation of NANOG, a transcription factor, which in turn promotes lung cancer stem cell-like characteristics and metastasis." (PMID 40799245, 2025). "To confirm these data, we evaluated the effect of MIR155HG on YBX1 ubiquitination in lung cancer cells, which showed that MIR155HG expression could increase the stability of YBX1 via reducing its ubiquitous modification." (PMID 39043648, 2024). "recently reported that the interaction between YBX1 and lncRNA RMRP could subsequently activate TGFBR1 expression in nonsmall cell lung cancer." (PMID 37867401, 2023). "These experiments revealed that the level of hY4F sorted into EVs was significantly reduced in the absence of YBX1 protein, indicating that YBX1 is necessary for the sorting and secretion of hY4F into lung cancer EVs." (PMID 35410432, 2022). "In previous studies, Y-box sequence, as a cis-acting element, up-regulated ceramide synthase 6 through the transcriptional regulation of YBX1 to promote lamellipodia formation as well as migration activity, and up-regulated TGFBR1 to promote the stemness and EMT of lung cancer cells." (PMID 34976785, 2021). "Furthermore, in mouse xenograft models and a lung cancer metastasis model, MUC1, which is downstream of YBX1, partially reversed the decreased number and size of tumors caused by YBX1 silencing." (PMID 34976785, 2021). "In conclusion, the o8G reader YBX1 increases circKIAA1797 stability and cytoplasmic distribution, and circKIAA1797 affects cuproptosis levels by regulating the FDX1-LIPT1-DLAT ternary complex and the opening and closing of the mPTP, which ultimately promotes the development of lung cancer." (PMID 40176113, 2025). "Mechanistically, CDKL1 interacted with the transcription factor YBX1 and decreased the binding affinity of YBX1 for the PD-L1 gene promoter, which consequently inhibits the expression of PD-L1, ultimately leading to the activation of CD8+ T cells and the inhibition of immune evasion in lung cancer." (PMID 38520004, 2024).
lung cancer (continued). "For example, lung cancer tissue samples expressed reduced lncRNA MIR22HG levels compared with normal lung tissues, and MIR22HG could accelerate lung cancer cell survival and cell death signaling by regulating the oncogenes YBX1, MET, and p21." (PMID 37304650, 2021). "CAR intergenic 10 (CAR10) a novel lncRNA, could bind and stabilize transcription factor Y-box-binding protein 1 (YB-1), leading to up-regulation of the epidermal growth factor receptor (EGFR) and proliferation of lung cancer cells, and CAR10-YB-1 represented a potential therapeutic target in NSCLC." (PMID 27992369, 2017). "In addition, rescue experiment indicated that YBX1 co-transfection recovered the downregulated proliferation and colony formation ability in SETD3 knockdown-A549 cells, suggesting YBX1 is the downstream of SETD3 mediated regulation of lung cancer cells proliferation." (PMID 35410432, 2022). "A proteomics analysis study suggests that the expression of cytokeratine 8, Y-box binding protein 1 (YB-1), proliferating cell nuclear antigen (PCNA), non-metastatic protein 23 (Nm23) were also significant in lung cancer development." (PMID 26061816, 2015).
gastric cancer (58 papers, 2013 to 2026). A primary or metastatic malignant neoplasm involving the stomach. "Specifically, the m5C reader protein YBX1 is overexpressed in gastric cancer cells and tissues resistant to 5-FU, and is linked to a poor prognosis." (PMID 41584846, 2025). "Previous studies have shown that YBX1 is highly expressed in advanced gastric cancer tissues and is associated with shorter disease-free survival, though the exact mechanisms by which YBX1 promotes cancer progression through binding to RNA m5C methylation regions remain to be elucidated." (PMID 40370440, 2025). "Moreover, YBX1 serves as a transcriptional activator and YBX1 activation was associated with cancer progression, including gastric cancer." (PMID 30286788, 2018). "Our results showed that HOXC-AS3 could bind to YBX1, thus transcriptionally regulating a large set of genes that are linked to cell proliferation and cell migration in gastric cancer cells, such as MMP7, WNT10B, and HDAC5, thus promoting GC cell proliferation and migration." (PMID 30286788, 2018). "For example, lncRNA PIN1P1 enhances YBX1 protein expression, promoting gastric cancer via PIN1 upregulation." (PMID 40799245, 2025). "CircFAT1 (e2) interacts with YBX1 to suppress the progression of gastric cancer by targeting miR-548g." (PMID 40799245, 2025). "LINC00665 binds to YBX1, activating Wnt3a/β-catenin signaling and promoting gastric cancer proliferation and metastasis." (PMID 40799245, 2025). "In gastric cancer, YBX1 upregulates the expression of SPP1, promoting gastric tumor-initiating cells through the ITGB1/YBX1/SPP1/NF-κB signaling pathway." (PMID 40799245, 2025). "This novel mechanism of GAS5 suppressing stomach carcinogenesis via the YBX1/p21 pathway serves as a potential target for the development of lncRNA-based therapeutics for the treatment of stomach cancer." (PMID 39941145, 2025). "Specifically, HOXC-AS3 binds to YBX1, leading to transcriptional regulation of multiple genes associated with cell proliferation and migration—such as MMP7, WNT10B, and HDAC5—in gastric cancer cells, thereby promoting malignant behaviors." (PMID 41312360, 2025). "USP10 deubiquitinates of YBX1 leading to increased apoptosis in gastric cancer cells and decreased resistance to oxaliplatin." (PMID 39605891, 2024). "CREB1-activated PIN1P1 contributes to gastric cancer progression by interacting with YBX1 and inducing PIN1 upregulation." (PMID 38255791, 2024). "Intriguingly, elevated levels of YBX1 in exosomes originating from gastric cancer are internalized by HUVECs, leading to increased expression of angiogenic factors, including IL-8, VEGF, ANGPT1, and MMP-9, at both the mRNA and protein levels." (PMID 38255791, 2024). "The upregulated long non-coding RNA (lncRNA) LINC00665 in gastric cancer interacts with YBX1, activating Wnt/β-catenin signaling, promoting tumor progression." (PMID 38255791, 2024). "For example, the regulatory effect ofHOXC-AS3 on HDAC5 expression is mediated through its interaction with YBX1, which facilitates the proliferation and migration of gastric cancer cells." (PMID 38899362, 2024). "We reveal that the pseudogene PIN1P1 promotes the progression of gastric cancer by interacting with YBX1 and activating PIN1." (PMID 37929660, 2024). "For instance, circFAT1(e2) inhibits gastric cancer progression by targeting miR-548 g in the cytoplasm and interacting with YBX1 in the nucleus." (PMID 38273320, 2024). "In contrast to most reports that circFAT1 was present in cytoplasm, it was present in cytoplasm to upregulating tumor suppressor RUNX1 by acting as a sponge for miR-548g, and in nuclei to regulate YBX1 function by physical interaction in gastric cancer." (PMID 35844799, 2022). "HOXC-AS3 has been shown to interact with Y-box binding protein-1 (YBX1), a transcription factor, in gastric cancer cells, and our bioinformatic analysis (RNAInter) identified this interaction in NSCLC cells as well." (PMID 35387975, 2022).
gastric cancer (continued). "In summary, our results demonstrate that type I collagen is capable of promoting the TIC phenotype in gastric cancer cells via the ITGB1/YBX1/SPP1/NF-κB signaling pathway." (PMID 34758833, 2021). "In this study, we examined the effect of YBX1 on gastric cancer cells and found that knockdown of YBX1 significantly inhibited the proliferation and clonal survival of both BGC823 and SGC7901 cells." (PMID 33247987, 2021). "The literature suggests that NOP2 is highly expressed in prostate cancer, gallbladder cancer, and lung adenocarcinoma, while upregulated YBX1 plays a significant protumourigenic role in breast, renal, and gastric cancer." (PMID 34394351, 2021). "YBX1 is involved in the antigen presentation pathway and phage maturation, which is related to gastric cancer and gastric epithelial cancer." (PMID 34476221, 2021). "Oncogene‐like effects of TMEM92‐AS1: LncRNA TMEM92‐AS1 regulates the expression of downstream target gene CCL5 by binding with YBX1 protein to play the role of oncogene and affects prognosis of patients with gastric cancer." (PMID 33247987, 2021). "Meanwhile, 3D cultured YBX1/SPP1 silenced gastric cancer cells showed a weakened ability to form colonies as well as diminished chemoresistance, indicating that 3D collagen promotes the TIC phenotype through YBX1 and SPP1." (PMID 34758833, 2021). "LncRNA HOXC-AS3 interacts with YBX1 to mediate gastric cancer tumorigenesis, and a 115 nucleotide region of HOXC-AS3 are responsible for its binding ability to YBX1." (PMID 33511127, 2020). "LncRNA GAS5 downregulation lowers YBX1 protein concentration, interfering with YBX1-transactivated p21 transcription and abrogating G1 phase cell cycle arrest in gastric carcinoma." (PMID 32489713, 2020). "Consistent with our finding, the regulatory effect of GAS5 on YBX1 was identified by a previous study on stomach cancer." (PMID 31534503, 2019). "lncRNA GAS5 down-regulation reduced the YBX1 protein level, which decreased YBX1-transactivated p21 expression and abolished G1 phase cell cycle arrest in stomach cancer." (PMID 25959498, 2015). "TMEM92-AS1 binds to YBX1, promoting gastric cancer progression through CCL5 upregulation." (PMID 40799245, 2025). "A prior study has revealed that HOXA10-AS may act as an oncogene by binding to miR-6509-5p, leading to the upregulation of Y-box binding protein 1 in gastric cancer." (PMID 41425708, 2025). "Furthermore, circ-SAR1A up-regulates YBX1 expression by binding to miR-382, facilitating the growth and invasion of renal cancer cells, while hsa_circ_0008035 participates in gastric cancer occurrence by targeting the miR-375/YBX1 axis." (PMID 40799245, 2025). "One study focusing on stomach cancer identified a mechanism wherein the depletion of GAS5 increased the turnover of transcriptional activator Y-box-binding protein 1 (YBX1) through direct interaction, thereby reducing p21 expression and subsequent G1 phase arrest." (PMID 39941145, 2025). "Similarly, HOXC-AS3 lncRNA mediates gastric cancer by binding to YBX1 and regulating cell proliferation and migration." (PMID 40799245, 2025). "GAS5 binds to YBX1, enhancing G1 cell cycle arrest in gastric cancer." (PMID 40799245, 2025). "Additionally, YBX1’s relevance to metastasis has been documented in various cancer types, including gastric cancer, skin squamous cell cancer, prostate cancer, ovarian cancer, and spinal chordoma." (PMID 38255791, 2024). "HOXC-AS3 was elevated in GC (gastric cancer) in a prior study by Erbao Zhang, and when combined with YBX1 could facilitate GC cell proliferation and migration." (PMID 36031658, 2022). "Moreover, suppression of YBX1 or SPP1 suppressed the activation of NF-κB in gastric cancer cells cultured in 3D gels, indicating that 3D collagen culture upregulated NF-κB expression through YBX1/SPP1 signaling." (PMID 34758833, 2021). "This indicates that ITGB1 might participate in gastric cancer progression through YBX1/SPP1 signaling." (PMID 34758833, 2021).